LINC01311 (long independently transcribed non-coding RNA 1311)
Gene: Long non-coding RNA gene on chromosome 22 (19,171,395 to 19,185,045, forward strand). Ensembl gene ENSG00000260924.
Diseases named in the same sentence as LINC01311 in open-access papers:
LINC01311 is named in the same sentence as 2 diseases in open-access papers, as found by Europe PMC text mining. Sharing a sentence is not in itself a finding about the gene and the disease. The quoted sentences say what the papers report.
liver cancer (1 paper, 2020). An epithelial or non-epithelial malignant neoplasm that arises from the liver. "In addition, LINC01311, another ip-lncRNA, was found to be up-regulated in liver cancer and metastatic prostate cancer." (PMID 32079618, 2020).
LINC01311 also shares sentences with these, for which no sentence is quoted: metastatic prostate carcinoma (1 paper).